RNU6-1329P (RNA, U6 small nuclear 1329, pseudogene)
Gene: Small nuclear RNA gene on chromosome 12 (92,952,639 to 92,952,745, forward strand). Ensembl gene ENSG00000202534.
Homologues: Orthologues: chimpanzee U6 (99% identical), mouse Gm26327 (84% identical), guinea pig U6 (83% identical). Paralogues in human: RNU6-11P (91% identical), RNU6-29P (91% identical), RNU6-37P (91% identical), RNU6-43P (91% identical), RNU6-25P (90% identical), RNU6-33P (90% identical), RNU6-48P (90% identical), RNU6-1 (89% identical), RNU6-2 (89% identical), RNU6-38P (89% identical), RNU6-39P (89% identical), RNU6-3P (89% identical), and 1288 more.